CXCR4 (C-X-C motif chemokine receptor 4)
Diseases named in the same sentence as CXCR4 in open-access papers (continued):
Sharing a sentence is not in itself a finding about the gene and the disease.
tumor (continued). "Similarly, since HIF-1α might regulate the expression of CXCR4, we examined the expression of HIF-1α in implanted tumor tissue." (PMID 27175473, 2016). "Therefore, the correlation of CXCR4 and CXCL12 expression levels and tumor invasiveness might be proposed as potential early diagnostic biomarkers." (PMID 26441831, 2015). "Furthermore, these collagen type I+/CXCR4+ cells were confirmed to produce FGF2, suggesting that the collagen type I+/CXCR4+ fibrocyte-like cells play an essential role in the bevacizumab resistance of tumours by expressing FGF2." (PMID 26635184, 2015). "However, blocking of the CXCL12-induced CXCR4-mediated signaling was not able to completely suppress tumor growth or eliminate all cancer cells." (PMID 26083776, 2015). "In these types of cancers, miR-494 functions its tumor suppressive effects, and inhibites cell proliferation, cell migration, and cell invasion and promoting apoptosis by regulating different oncogenes in different cancer cells, such as VEGF, CXCR4, CLPTM1L, HOXA10, and c-MYC." (PMID 26317788, 2015). "However, this iv model did not confirm the abrogative effect of CXCR7 on CXCR4-mediated tumor growth observed in our orthotopic NB model." (PMID 25955316, 2015). "Indeed, studies in other tumor models revealed either a role for CXCR4, but not for CXCR7, in metastases induction, or the enhanced metastatic potential conferred by CXCR7." (PMID 25955316, 2015). "Additionally, IL-24 inhibited tumor cell migration both in the presence and absence of the CXCR4 agonist, SDF-1." (PMID 25775124, 2015). "In support of these results, our study indicated that CXCR4 expression was significantly correlated with both lymph node metastasis and an unfavorable prognosis in resected PDAC and further supported the important role of tumor–stroma interactions in PDAC progression." (PMID 25679210, 2015). "The higher CXCR4 protein levels in ATC compared to those in TC could be responsible for the higher nodal metastasis rate, earlier recurrence, and enhanced aggressiveness of the ATC tumor entity." (PMID 25671300, 2015). "In addition, although CXCR4 protein expression did not change according to rs2228014 genotype distribution (p = 0.757), higher protein expression in the tumor microenvironment compared with adjacent normal breast tissue (p = 0.01) was verified." (PMID 26576337, 2015). "CXCL12/CXCR4 axis acts on the tumor microenvironment through the modulation of the expression and secretion of other CKs (i.e., CCL2, CXCL8) and, concomitantly, CXCR4 expression could be influenced by cytokines (TNFα, IFNγ, IL4-6-10) produced by cells in the microenvironment." (PMID 24904289, 2014). "There are evidences that tumor cells express a high level of CXCR4 and that tumor metastasis target tissues (lung, liver, and bone) express high levels of the ligand CXCL12, allowing tumor cells to directionally migrate to target organs via a CXCL12-CXCR4 chemotactic gradient." (PMID 24810923, 2014). "Taking into consideration that the majority of the CXCR4 and VEGFR-3 measurements, according to the literature, have been performed on tumour tissues after curative gastrectomy, we could expect an increase of the expression of these molecules in patients who are treated in a palliative setting." (PMID 24981311, 2014). "Interestingly, treatment with CXCR4 antagonist Plerixafor reduced proliferation, invasion, and extracellular signal-regulated kinase 1/2 (ERK1/2) signaling, thus sensitizing tumor cells toward cytoreductive chemotherapy in two colon cancer cell lines (HT-29 and SW480)." (PMID 24971349, 2014). "However, some cell types, especially endothelial and distinct tumor cells, express the two CXCL12-receptors, CXCR4 and CXCR7, in combination and they may regulate one another’s function." (PMID 24770893, 2014).
tumor (continued). "Furthermore, this study demonstrates that macrophages are recruited and polarized by signals emitted by MM and BMSCs and recognize the CXCR4/CXCL12 axis as a critical regulator of MM-stroma interactions, shaping the MM tumor niche and contributing to the microenvironment formation." (PMID 25526031, 2014). "ALDH1 enzyme activity defines a subpopulation of tumor cells which exhibit stem cell-like properties and whose prevalence correlates with survival in PC Additionally, a number of cell surface markers are co-expressed with ALDH1, such as CD44, CD24, CD133, and CXCR4." (PMID 24652403, 2014). "However, CD8+ cells anywhere in the tumour did not express CXCR4, demonstrating that their distribution was not mediated by this interaction." (PMID 24961933, 2014). "We have also shown that VIM-positive (CK19−/VIM+) CTC-enriched blood fractions, unlike CK19+/VIM− fractions, show elevated CXCR4 and uPAR levels, which might contribute to more aggressive tumor characteristics." (PMID 24709997, 2014). "Previous study also showed that tumor cells express a high level of CXCR4 and that tumor metastasis target tissues (lung, liver, and bone) express high levels of the ligand CXCL12, allowing tumor cells to directionally migrate to target organs via a CXCL12-CXCR4 chemotactic gradient." (PMID 24810923, 2014). "In tumor biopsy samples, there is no clear negative correlation of promoter methylation with mRNA expression indicating that DNA methylation is not the only mechanism for downregulation of CXCR4 transcription." (PMID 25114911, 2014). "4EGI-1 treated tumor cells presented decreased CSC pluripotency markers NANOG and OCT4, tumor metastasis regulator CXCR4, EMT mediator c-MYB and proangiogenic factor VEGF, but not translation initiation factors eIF1A or eIF5, comparing to vehicle treated breast CSC tumor cells in vivo." (PMID 25115391, 2014). "Whether a human tumor viral oncogene could regulate tyrosine sulfation of CXCR4 has not yet been examined." (PMID 23472069, 2013). "Because of the dichotomy of clinical outcomes observed for SHH MB, we first investigated whether the expression profiles of CXCL12 and CXCR4 in SHH and non-SHH MB is associated with tumor histology (desmoplastic vs. non-desmoplastic) and clinical outcome." (PMID 23497290, 2013). "However, results from experiments examining the potential of CXCR4− or CXCR7-expressing subpopulations to establish tumors in vivo, indicated that tumor formation is independent of the presence of CXCR4 or CXCR7." (PMID 23555768, 2013). "This EGFR-mediated increase of CXCR4 appears to be mediated by phosphatidylinositol 3-kinase/PTEN/AKT/mTOR signal transduction pathway, and by the activation of hypoxia inducible factor (HIF) 1α, a transcription factor that allows tumor to prosper under conditions of low oxygen tension." (PMID 23322021, 2013). "Our results suggest that the expression levels of MIF and CXCR4 were altered in the same way in different cell populations in the tumor microenvironments of ESCC and that the CXCR4 protein was a receptor response to MIF signaling in both immune cells and tumor cells." (PMID 23497377, 2013). "However, co-expression of CXCR4 and CXCR7 in OS tumor tissue did not change the predictive power for a tendency of poor outcome that was also already evident when CXCR4 immunostaining was analyzed alone." (PMID 24040160, 2013). "We have previously demonstrated that tumor models, which more accurately represent the modest five-fold CXCR4 over-expression found in the clinical situation, such as the MIN-O model used in this study, better represent the clinically found CXCR4 expression levels in tumors." (PMID 23326303, 2013). "In addition to the observed lack of correlation between HIF-1α and CXCR4 protein expression within individual tumor samples, culture of cell lines under hypoxic conditions did not affect CXCR4 surface expression." (PMID 23249693, 2012). "Of the 241 samples, none were negative for CXCR4 in tumour cells." (PMID 22415233, 2012).
tumor (continued). "The Neu-YD and Neu-NDL tumor cells were not significantly affected by AMD3100 inhibition of CXCR4." (PMID 22314082, 2012). "Hypothesising that the expression of CXCR4 and/or HER2, their respective pathways and their interaction are involved in mediating tumor progression and metastatic homing, each therapeutic group was evaluated separately as to the intensity of HER2- and CXCR4-expression levels." (PMID 23082154, 2012). "Additional NF-κB target genes which contribute tumor cell migration and/or metastasis include cellular adhesion molecular, such as ICAM-1 and VCAM-1; matrix metalloproteinases, such as MMP-9; chemokine receptors, such as CXCR4, and vascular endothelial growth factor (VEGF)." (PMID 22952718, 2012). "Consequently, K5 down-regulated the down-stream genes expression of CXCR4 and VEGF, which may be responsible for the dual inhibitory effects of K5 on angiogenesis and tumor metastasis." (PMID 23300882, 2012). "Similarly, none of the herbal medicines had significant effects on CXCR4 or CCR5 expression in tumor cells." (PMID 22690248, 2012). "Analysis of CXCR4 was possible in 241 of the 360 cores (67%), with the remainder not available on the cut slide, being lost during antigen retrieval or not demonstrating viable tumour cells in the core." (PMID 22415233, 2012). "In addition, we found significant differences between positive and negative CXCL12/CXCR4 samples in regards to the following clinicopathological features: i) lymph node metastasis and ii) tumor TNM staging." (PMID 23181100, 2012). "However, they may also promote angiogenesis, proliferation and tumor cell invasion, such as the CXCL12 (SDF-1)/CXCR4 axis." (PMID 22180778, 2011). "Accordingly, over-expression of ZEB2 and TWIST1 in surgical samples of both normal and tumor tissues can induce EMT, resulting in over-expression of representative EMT markers VIM, FN, and COLs and membrane signal transducers IL8, CXCL4, CCL5, CXCR4, PDGFRB, and TLR2." (PMID 21533028, 2011). "Interestingly, lymphatic endothelial cells promoted the migratory activity of CXCR4+/CD133+ tumor cells, but not those of CXCR4 tumor cells." (PMID 24212647, 2011). "Based on our in vitro results CRC patients with metastasis may be expected to express more CXCR4 in their tumor cells compared to CRC patients without metastasis." (PMID 21349176, 2011). "In addition, when considering inhibitors of CAIX, LOX, or CXCR4, selection of patients should be based on examination of expression levels of these target genes in tumor biopsies or by PET imaging based on tumour retention of radiolabeled antibodies (for example, against CAIX)." (PMID 22128892, 2011). "Suppression of tumor growth is most likely achieved by the induction of MKP-1 which leads to the down-regulation of p38MAPK and ERK1/2, a PPARγ-independent event; retardation of metastases is via a PPARγ-dependent pathway which directly decreases CXCR4 and MMP expressions." (PMID 20226009, 2010). "HIF-1α activation correlates with metastasis and can promote metastasis through the regulation of key factors governing tumor cell metastatic potential, including E-cadherin, lysyl oxidase (LOX), connective tissue growth factor (CTGF), and plasminogen activator inhibitor-1 (PAI-1), CXCR4." (PMID 20953377, 2010). "Furthermore, we have demonstrated that blockade of CXCR4 at metastatic steps that follow entrance of malignant cells into the circulation is sufficient to reduce metastasis, although we cannot rule out a role for CXCR4 in escape from the primary tumor." (PMID 20849618, 2010). "Differences in CXCR4 expression in adjacent liver tissue and tumor tissue of HCC without PVTT." (PMID 21110890, 2010). "The mechanisms by which CXCR4 regulate tumor progression are yet not clear." (PMID 19340288, 2009). "Of the 181 tumor samples examined, 91 (50.3%) were positive for CXCR4 and 90 (49.7%) were negative." (PMID 19508713, 2009).
tumor (continued). "Here we show that CXCR4 up-regulates the expression of the chemokine CCL20 in various cancer cells, and that CCL20 in turn promotes in an autocrine manner the survival, proliferation and adhesion of cancer cells in vitro and enhances xenograft tumor growth, vascularization and invasion in vivo." (PMID 19340288, 2009). "However, it should be noted that in the majority of tumors CXCR4 immunostaining was heterogeneously distributed throughout the tumor and not uniformly present on all tumor cells." (PMID 19116653, 2008). "Although in this study we focused on the effect of VHL inactivation on CXCL12/CXCR4-mediated organ-specific metastases, it is possible that other hypoxia-inducible genes under the control of HIF-1α/VHL pathway may also play a role in tumor metastasis." (PMID 17083723, 2006). "Interestingly, it has been demonstrated that both RCC cell lines and human RCC tumor specimens express elevated levels of CXCR4, but not its ligand CXCL12, as compared to normal kidney specimens." (PMID 17083723, 2006). "In addition, high expression of CXCR4 on the surface of activated CD4 + T cells may lead to the production of cytokines that affect T-cell activation, thereby promoting the initiation of an effective anti-tumour response." (PMID 41243106, 2025). "Taken together these data support our hypothesis that engagement of CXCR4 or S1P5 with their cognate ligands creates a positive feedback loop driving one another’s upregulation, in line with our proposed model of S1P1/5 and CXCR4-mediated NK cell desensitization to stimulation by tumor cells." (PMID 40155684, 2025). "At least one study of 19 patients shows that it is useful for assessing the presence of CXCR4 receptors in this tumor and may have future potential in this area, with various peptides (most prominently 177Lu-Lu-DOTAT-POL3026) being shown to have activity against CXCR4-bearing tumor cells in vitro." (PMID 40002288, 2025). "Moreover, we observed a reduction in the percentage of epithelial (i.e., EpCAM+) cells within the tumor, and a significant decrease in the percentages of CD133+ and CD133+/CXCR4+ cells within the EpCAM+ cell population, which is in line with our hypothesis that Ru1 affects the CSC compartment." (PMID 38281027, 2024). "This may be responsible for the faster tumor progression and more aggressive disease seen in HIV-infected patients with HNSCC; however, this needs to be confirmed in a larger study to see if HIV-positive patients with HN cancer may benefit from therapies targeting CXCR4." (PMID 39001265, 2024). "In addition, the formation of mitochondria-dependent vital NETs by silent information regulator 1 (SIRT1) that has been reported in both tumour-associated aged neutrophils (Naged, CXCR4+ CD62L low) in breast cancer lung metastasis and non-tumour pathologies has not been studied in preeclampsia." (PMID 38794175, 2024). "The increased exposure of neoantigens and expression of chemokines in tumor cells induced by radiotherapy may offer new avenues for CAR-NK therapy development, such as CARs targeting NKG2DL or overexpressing chemokine receptors (CXCR1, CXCR2, and CXCR4) through CAR design." (PMID 38162672, 2023). "Moreover, high MRP2/CXCR4/PD-L1 co-expression could have a prognostic value for GBC regardless of tumor staging." (PMID 37444550, 2023). "When examining the factors that could contribute to CD8+ Teff tumor recruitment, we found that CD8+ Teffs expressed the chemokine receptors CXCR3 and CXCR4, while the TME produced abundant CXCL9 and CXCL12, which are the key chemokines known to bind CXCR3 and CXCR4, respectively." (PMID 35552271, 2022). "On the other side, we observed a trend that association between high CXCR4 tumor expression in recurrent cancer biopsies and better RFS, what might indicate that in recurrent disease the biology of the tumor itself is the most crucial factor for prognosis and not the immune response." (PMID 35397601, 2022).
tumor (continued). "Relative to [18F]FDG, however, CXCR4 PET has already identified a higher number of atherosclerotic lesions in the vessel wall in oncology patients and, thus, may even provide a more reliable read-out of ongoing inflammatory activities under tumor-specific treatment." (PMID 35674738, 2022). "Hence, miR-146a, which is highly up-regulated in EBV-associated tumor cells, is reported to down-regulate the expression of CXCR4, a process that may participate, together with viral proteins (e.g., latent membrane protein-1 LMP1), in the immune evasion of EBV-tumor cells." (PMID 35159113, 2022). "Interestingly, a large percent of HNSCC patients could be candidates to targeted nanotoxin therapy since in our 17-patient cohort, 88.2% were positive for the CXCR4 receptor, 94% of them expressed GSDME in tumor tissue, whereas 87% of GSDME+ tumors also co-expressed CXCR4." (PMID 35120582, 2022). "CXCR7, but not CXCR4, expression can be increased by lipopolysaccharide treatment in cells expressing both TLR4 and the MD2 coreceptor; additionally, in patients, high expression of TLR4, MD2 and CXCR7 is associated with tumor cell infiltration in lymph nodes and distant metastases." (PMID 35406582, 2022). "[111In]G5-X4 showed similar uptake in CXCR4 positive and negative tumors at comparable levels detected for [111In]G5-Ctrl at 24 h that is most likely attributed to prolonged circulation and significant passive tumor targeting due to the enhanced permeability and retention (EPR) effect." (PMID 35336029, 2022). "Besides the CXCR4/CXCL12 axis, other studies have implicated the CCL2/CCR2 axis in vitro and in animal models, although the experimental design used in these studies more specifically addressed tumor growth into bones rather than homing from distant sites." (PMID 33671469, 2021). "We investigated whether TNC influenced expression of the CXCL12 receptors CXCR4 and/or CXCR7 and observed that Cxcr4 levels were higher in TNC‐low (WT/shTNC, KO/shTNC) tumors and in cultured tumor cells upon TNC knockdown, revealing an opposite regulation than Cxcl12 by TNC." (PMID 33988305, 2021). "Moreover, transcription factor hypoxia-inducible factor 1-alpha (HIF1α) and the biological interaction between HER2 and CD44 may lead to upregulation of C-X-C chemokine receptor type 4 (CXCR4), which promotes tumor progression and NCRT resistance in gastroesophageal cancer." (PMID 33151397, 2021). "Moreover, targeting CXCR4 or CXCR7 alone is not sufficient for inhibiting CXCL12-mediated pro-metastatic responses suggesting that compensatory pathways induced by these receptors can allow tumor escape." (PMID 34298991, 2021). "Additionally, CCR4/CCL17 or 22 and CXCR4/CXCL12 are vital chemokine signalling pathways for the recruitment of immune cells (regulatory T cells (Tregs), neutrophils and dendritic cells (DCs)) and participate in the metastatic colonization of tumour cells as well." (PMID 35006432, 2021). "Interestingly, CXCL12 enhances the expression of VE-cadherin, matrix metalloproteinase 2 (MMP2) and laminin5γ2 via CXCR4 in tumor cells (rather than endothelial cells), forming vascular-like channels that promote vascular mimicry (VM) formation and provide blood perfusion for HCC tissues." (PMID 34386499, 2021). "The involvement of the CXCR4/CXCL12 signaling axis in the pathogenesis of several types of cancers was expected considering its implication in both cell migration and regulation of interactions with components of the tumor microenvironment, a function that may ultimately regulate metastasis." (PMID 33081391, 2020). "Moreover, the relatively low tumor uptake may be partly explained by the fact that CXCR4 is not a tumor-specific antigen." (PMID 32321944, 2020).